RPL31P12 (ribosomal protein L31 pseudogene 12)
Synonyms: RPL31_1_62
Gene: Processed pseudogene on chromosome 1 (72,301,472 to 72,301,829, forward strand). Ensembl gene ENSG00000227207.
Diseases named in the same sentence as RPL31P12 in open-access papers:
RPL31P12 is named in the same sentence as 4 diseases in open-access papers, as found by Europe PMC text mining. Sharing a sentence is not in itself a finding about the gene and the disease. The quoted sentences say what the papers report.
depression (4 papers, 2018 to 2025). "Interestingly, the SNP rs10789340 in RPL31P12 was also identified as a potential risk locus, further corroborating its role in obesity-depression comorbidity." (PMID 40405979, 2025). "SMR analysis results identified NEGR1 and RPL31P12 as genetic links affecting the interaction between depression and obesity." (PMID 40405979, 2025). "We identified RPL31P12, NEGR1, and DCC as common risk genes for obesity and depression." (PMID 40405979, 2025). "Individual genes that commonly emerge among these studies include those with existing links to depression, such as DRD2 and FADS1, as well as novel genes such as NEGR1 and RPL31P12 without existing links to depression." (PMID 37076454, 2023).
Stroke (1 paper, 2021). Sudden impairment of blood flow to a part of the brain due to occlusion or rupture of an artery to the brain. "Cross-trait meta-analyses and fine-mapping of transcriptome-wide association signals identified novel risk genes for MDD and stroke, including RPL31P12, BORSC7, PNPT11, and PGF." (PMID 34859065, 2021).
RPL31P12 also shares sentences with these, for which no sentence is quoted: Obesity (2 papers); anorexia nervosa (1).